CENPT (centromere protein T)
Description:
Component of the CENPA-NAC (nucleosome-associated) complex, a complex that plays a central role in assembly of kinetochore proteins, mitotic progression and chromosome segregation. The CENPA-NAC complex recruits the CENPA-CAD (nucleosome distal) complex and may be involved in incorporation of newly synthesized CENPA into centromeres. Part of a nucleosome-associated complex that binds specifically to histone H3-containing nucleosomes at the centromere, as opposed to nucleosomes containing CENPA. Component of the heterotetrameric CENP-T-W-S-X complex that binds and supercoils DNA, and plays an important role in kinetochore assembly. CENPT has a fundamental role in kinetochore assembly and function. It is one of the inner kinetochore proteins, with most further proteins binding downstream. Required for normal chromosome organization and normal progress through mitosis.
Synonyms: CENP-T; C16orf56; FLJ13111; SSMGA
Tractability: PROTAC: ubiquitination databases record sites on it.
Gene: Protein-coding gene on chromosome 16 (67,828,157 to 67,847,811, reverse strand). Ensembl gene ENSG00000102901.
Subcellular location: Nucleus; Chromosome, centromere; Chromosome, centromere, kinetochore
Subcellular location (Human Protein Atlas): Nuclear bodies; Nucleoplasm
Pathways (Reactome):
Cell Cycle: Amplification of signal from unattached kinetochores via a MAD2 inhibitory signal; Deposition of new CENPA-containing nucleosomes at the centromere; EML4 and NUDC in mitotic spindle formation; Mitotic Prometaphase; Resolution of Sister Chromatid Cohesion; Separation of Sister Chromatids
Signal Transduction: RHO GTPases Activate Formins
Gene Ontology:
Molecular function: protein binding; DNA binding; protein heterodimerization activity
Biological process: chromosome organization; chromosome segregation; kinetochore assembly; mitotic cell cycle
Cellular component: chromosome, centromeric region; inner kinetochore; kinetochore; nuclear body; nucleoplasm; cytosol; nucleus
Genetic constraint (gnomAD): Loss-of-function variants: 42 observed, 59.27 expected, observed/expected ratio (o/e) 0.71, 90% interval 0.55 to 0.92. The upper end of that interval is the gene's LOEUF score, 0.92, which puts it in group 3 of 6, group 1 being the genes least tolerant of losing a copy. Missense variants: 715 observed, 722.4 expected, observed/expected ratio (o/e) 0.99, 90% interval 0.93 to 1.05. Synonymous variants: 295 observed, 292.83 expected, observed/expected ratio (o/e) 1.01, 90% interval 0.92 to 1.11.
Homologues: Orthologues: macaque CENPT (93% identical), chimpanzee CENPT (88% identical), pig CENPT (75% identical), dog CENPT (72% identical), guinea pig CENPT (58% identical), mouse Cenpt (56% identical), rat Cenpt (54% identical), zebrafish cenpt (27% identical), tropical clawed frog cenpt (25% identical).
Diseases named in the same sentence as CENPT in open-access papers:
CENPT is named in the same sentence as 15 diseases in open-access papers, as found by Europe PMC text mining. Sharing a sentence is not in itself a finding about the gene and the disease. The quoted sentences say what the papers report.
microcephaly (2 papers, 2017 to 2020). A congenital or acquired developmental disorder in which the circumference of the head is smaller than normal for the person's age and sex. "In summary, we identified a homozygous splice-site mutation in CENPT and confirmed its aberrant splicing effect at the transcript level in two siblings with severe microcephaly and short stature born to consanguineous parents from Turkey." (PMID 29228025, 2017). "The biallelic defect of CENPT in humans has been reported to cause severe growth failure and microcephaly but not to cause chromosome number instabilities, which differed from the phenotypes of our patient." (PMID 33094908, 2020). "Because the biallelic defect of CENPT causes a syndrome characterized by severe growth failure and microcephaly without chromosome number instabilities, which differed from the patient's phenotypes, we further investigated the CDC20 variant in this study." (PMID 33094908, 2020).
growth deficiency (1 paper, 2017). "In conclusion, the present study highlights CENPT as a novel disease gene and is the first to suggest the involvement of a constitutive and inner kinetochore/CCAN member in the pathogenesis of severe growth deficiency." (PMID 29228025, 2017).
kidney cancer (1 paper, 2025). Primary or metastatic malignant neoplasm involving the kidney. "Consistent with the TCGA RNA expression data analysis results, the expression of CENPT is significantly upregulated in kidney cancer tissues (p < 0.05)." (PMID 40651948, 2025). "In addition, we also collected 10 pairs of kidney cancer and paraneoplastic tissues in our center and determined the expression level of CENPT in these patient tissue samples." (PMID 40651948, 2025).
primordial dwarfism (1 paper, 2017). "Here, we report the addition of an inner kinetochore member CENPT (MIM:*611510), which is vital for kinetochore assembly, to the repertoire of genes implicated in primordial dwarfism." (PMID 29228025, 2017).
renal carcinoma (1 paper, 2025). A carcinoma arising from the epithelium of the renal parenchyma or the renal pelvis. "Here we show that Centromere Protein T (CENPT) is highly expressed in renal carcinoma (RCC) and promotes the tumor proliferation and metastasis of RCC." (PMID 40651948, 2025).
Smith-Magenis syndrome (1 paper, 2021). Smith-Magenis syndrome (SMS) is a complex genetic disorder characterized by variable intellectual deficit, sleep disturbance, craniofacial and skeletal anomalies, psychiatric disorders, and speech and motor delay. "These include a region located within the MHC, another located on chromosome 17 containing DLG2, TOM1L2, and overlapping the Smith-Magenis syndrome deletion, and another on chromosome 16 containing CENPT and PRMT7." (PMID 33646943, 2021).
cancer (4 papers, 2020 to 2025). A tumor composed of atypical neoplastic, often pleomorphic cells that invade other tissues. "We examined the mutations of both CDKAL1 and CENPT in different BC cell lines using the Cancer Cell Line Encyclopedia (CCLE) online database." (PMID 38217005, 2024). "All in all, CENPT-GCLC-GSH positive feedback loop gave us an improved understanding of the role played by GSH in cancer microenvironment." (PMID 40651948, 2025). "Our findings indicated that CENPT’s hazard ratio (HR) ranks among the top five, and its role in cancer has not been previously elucidated." (PMID 40651948, 2025). "The four histone modification-related genes highlighted, including DPY30, CBX8, CENPT, and PADI1, have been reported to have the potential to regulate the occurrence and development of cancer to some extent by altering the histone modification of cancer-related genes." (PMID 34090418, 2021). "The role of CENPT in cancers had not been previously elucidated." (PMID 40651948, 2025).
tumor (2 papers, 2021 to 2025). "We then investigated the underlying mechanism that CENPT increased the development of tumor." (PMID 40651948, 2025). "To further substantiate the impact of CENPT on the survival of tumor-bearing mice, we injected CENPT stably overexpressed Caki-1/786-O cells or corresponding controls into the subcutaneous right forelimbs of nude mice." (PMID 40651948, 2025). "Overexpression of GCLC almost completely rescued the inhibitory effects of CENPT silencing on mouse tumor growth." (PMID 40651948, 2025). "Colony formation experiments further demonstrated that CENPT overexpression significantly enhanced cell proliferation, indicating a promotion of tumor growth in vitro." (PMID 40651948, 2025). "At the protein level, CENPT expression was relatively higher in tumor tissues of 8 RCC patients than in matched paraneoplastic tissues (p < 0.001)." (PMID 40651948, 2025). "Therefore, CENPT plays an important role in the integrity of the genetic material of cells during mitosis, and its aberrant expression may lead to tumor progression." (PMID 34090418, 2021). "In summary, these results strongly indicate that CENPT markedly promotes the progression of RCC and shortens the survival period of tumor-bearing mice." (PMID 40651948, 2025). "Compared with CBX8 and DPY30, CENPT and PDAI1 have been less reported on promoting tumor development by influencing histone modification." (PMID 34090418, 2021). "However, overexpression of GCLC almost completely rescued the inhibitory effects of CENPT silencing on GSH levels in mouse serum and tumor tissues." (PMID 40651948, 2025). "In addition, overexpression of CENPT had the capacity to increase the GSH levels in mouse serum and tumor tissues." (PMID 40651948, 2025). "Additionally, the in vivo results also showed that overexpression of CENPT 168–561 could not promote RCC tumor growth, compared to the full-length CENPT overexpression group." (PMID 40651948, 2025).
CENPT also shares sentences with these, for which no sentence is quoted: cocaine dependence (1 paper); infection (1); liver cancer (1); nicotine dependence (1); opioid dependence (1); pancreatic cancer (1); renal cell carcinoma (1).